LINC02739 (long independently transcribed non-coding RNA 2739)
Gene: Long non-coding RNA gene on chromosome 11 (59,560,117 to 59,566,283, reverse strand). Ensembl gene ENSG00000255008.
Gene Ontology:
Molecular function: triplet codon-amino acid adaptor activity
Biological process: translation